MMP2 (matrix metallopeptidase 2)
Diseases named in the same sentence as MMP2 in open-access papers (continued):
Sharing a sentence is not in itself a finding about the gene and the disease.
tumor (continued). "MMP-2 and MMP-9 are enzymes that are implicated in the malignant progression of many tumor types." (PMID 26444270, 2015). "In the present study, we used an aCPP construct that could only be activated if the linker between the CPP and polyanionic peptides is cleaved by MMP2 secreted by tumour cells." (PMID 25671640, 2015). "Knockdown of ALDH1A3 by shRNA constructs could markedly down-regulate these tumor invasion associated genes (SNAIL, SLUG and MMP2), and the abilitie of cell invasion was also reduced in vitro." (PMID 26575197, 2015). "The major MMPs involved in tumor angiogenesis are MMP-2 and MMP-9." (PMID 26597177, 2015). "In addition, MMP-2 was increased when tumor cells had invaded the adipocyte-containing stroma surrounding a primary tumor, as would be predicted from our observations." (PMID 25747684, 2015). "In view of these findings, we speculate that specific factors from the tumor microenvironment are critical for MMP2 activation by sNEDD4." (PMID 25823820, 2015). "In addition, fibroblasts in omentum that have been activated by tumor cells have been shown to promote ovarian invasiveness via MMP-2 overexpression." (PMID 26426054, 2015). "Interestingly, we found that rapamycin inhibited mTOR signaling in addition to simultaneously downregulating the expression of CD44, SOX2 and MMP-2 and that it affected cell growth and tumor size and weight both in vitro and in vivo." (PMID 26202311, 2015). "Furthermore, the bevacizumab-treated tumor contained significantly more tumor cells that stained for the EMT markers matrix metalloproteinase 2 (MMP2), Zinc-finger E box-binding homeobox 1 (Zeb1), Zeb2, Snail, Slug and Twist." (PMID 25957416, 2015). "Therefore, the present meta-analysis pooled MMP-2 expression in stromal cells and tumor cells together." (PMID 25816052, 2015). "Moreover, OCT4B enhanced angiogenesis by the upregulation of CD34, VEGF, HIF-1α and IL-6, and promoted tumor cell mobility to the surrounding tissue by the upregulation of MMP2 and MMP9, and the induction of epithelial-mesenchymal transition (EMT)." (PMID 25816351, 2015). "Taking the SCRN1 function as a regulator of exocytosis in other cell types into consideration, we hypothesized that SCRN1 may enhance the secretion of MMP-2/9 to promote cancer cell invasion and tumor metastasis." (PMID 25814779, 2015). "Therefore, we focused on MMP9 and MMP2 expression because they are the enzymes responsible for tumor invasion." (PMID 25774514, 2015). "Important in the design of this imaging agent is the use of two luminophores that are tethered by a specific peptide with a hairpin-motive that ensured close proximity of the two while also having a specific amino acid sequence available for enzymatic cleavage by tumor-related MMP-2/9." (PMID 25985157, 2015). "PCR analysis of control (SAH) and experimental (SAM) treated LM-7 cells showed a marked inhibition in the expression of tumor-promoting genes (MMP-2, MMP-9, VEGF, PAI-1, and uPA) and genes (uPA, TFG-β, and RUNX2) which are known to promote the development and progression of skeletal metastasis." (PMID 25619880, 2015). "Additionally, tumor volume and weight are significantly inhibited through the suppression of Akt, mTOR, and Stat3, accompanied by a decrease in the expression of MMP-2 and MMP-9 in vivo." (PMID 26202311, 2015). "Increased MMP2 expression predicts tumor recurrence and unfavorable outcomes in NSCLC." (PMID 26388610, 2015). "Moreover, GLUT1 suppression in B16 cells led to a significant reduction of the expression of matrix metalloproteinase 2 (MMP2), which encodes for an enzyme involved in degradation of extra-cellular matrix proteins and tumor progression." (PMID 26293674, 2015).
tumor (continued). "In addition, we showed that FTY720 significantly decreased the intracellular enzymatic activity of SPHK1 and the expression level of MMP-2 and VEGF-A, both of which are closely linked to tumor invasion, metastasis, and angiogenesis." (PMID 26311741, 2015). "Finally, it is needed to point out that some experiments have shown that MMP2 provide a favorable environment for initiation of angiogenesis especially in tumor vessel formation, and it seems that high MMP2 expression benefits from angiogenesis." (PMID 25695105, 2015). "Also they are known to participate in angiogenesis and tumor growth particularly gelatinases (gelatinase A, MMP2, gelatinase B, and MMP9)." (PMID 25135219, 2014). "Both in vitro and in vivo experiments showed PDGF-D could promote tumor growth and invasion through up-regulating MMP2/9 and inducing EMT." (PMID 24646915, 2014). "Positive MMP-2 immunostaining was observed in the cytoplasm of tumor cells." (PMID 24690154, 2014). "MMP-2 and MMP-9 are the important proteins associated with tumor cells invasion characteristic." (PMID 25298750, 2014). "The expression of MMP-2 within the primary tumor was immunohistochemically examined." (PMID 24690154, 2014). "MMP-2 degrades the intercellular matrix, as well as the major component of basement membrane, collagen IV, thereby hydrolyzing the basement membrane, which allows tumor cells to enter the connective tissue." (PMID 25295105, 2014). "Activation of oncogenic K-Ras in oral cavity may thus represent early stages of tumor progression suggesting a possible inducing effect of the Ras oncogene on metastasis by activation of MMP-2/type IV collagenase." (PMID 24591757, 2014). "In accordance with earlier studies, the present data showed that X-ray radiation enhanced the secretion of VEGF, a potent angiogenic growth factor, as well as that of MMP-2 and -9, which degrade the basement membrane and extracellular matrix during tumor cell invasion and metastasis." (PMID 24893038, 2014). "As MMP-2 plays multiple roles in tumor in vivo, wogonin could inhibit the metastasis process through the suppression of MMP-2 expression and activity." (PMID 25203554, 2014). "MMP-14 is important within the MMP family, for its ability to activate other members, including the cell-surface expressed MMP-2, which may be critically involved in accelerating malignant processes, such as tumor metastasis." (PMID 24765144, 2014). "Wang and his colleagues reported that overexpression of Aurora-A contributes to the malignancy development of ESCC by enhancing tumor cell invasion as well as MMP-2 activity and expression, which can occur through signaling pathways involving p38 MAPK and Akt protein kinases." (PMID 25428915, 2014). "Interestingly, most of the TLX-expressing cells also expressed MMP-2 that is secreted in large amounts, likely to facilitate ECM degradation and tumor dissemination, a hallmark of advanced stages of NB." (PMID 25356871, 2014). "Univariate regression analysis showed that tumor stage (p = 0.027), presence of nodal (p = 0.018) and distant metastases (p = 0.006), tumor resectability (p = 0.002), and presence of MMP-2 expression in normal colorectal cells (p = 0.030) were significant factors for patients’ 2-year survival." (PMID 24395652, 2014). "Obtained results may suggest that the main source of MMP-2 in cancer tissue is rather interstitial inflammatory cells from tumor microenvironment than malignant tumor cells." (PMID 24395652, 2014). "Furthermore, knockdown of HIF-1α expression by adenovirus-mediated small hairpin RNA (shRNA) inhibits the angiogenesis and invasion in HCC cells and as a result, the levels of VEGF and MMP-2 are also repressed in endothelial cells transferred to the tumor." (PMID 25101278, 2014). "Recent studies showed that SFN inhibited MMP-2 expression in some tumor cell lines." (PMID 24587385, 2014).
tumor (continued). "To further test whether solanine can affect tumor metastasis, we determined the level of tumor metastasis related marker proteins, MMP-2 and MMP-9, in Panc-1 and SW1990 cells." (PMID 24949471, 2014). "MMP-2 favors tumor cells attachment through the changes they mediate in ECM." (PMID 25303976, 2014). "The average histoscore of MMP-2 expression per tumor was 98.9160 (standard deviation (SD) 50.1750)." (PMID 25097794, 2014). "Since matrix metalloproteinase-2 (MMP-2) is an important marker of tumor malignancy, we developed an original drug design strategy, MMP-2 activity dependent anchoring probes (MDAP), for use in MMP-2 activity imaging, and evaluated the usefulness of this probe in in vitro and in vivo experiments." (PMID 25010662, 2014). "Additionally, PMNs have been described to promote tumour progression by activating matrix metalloproteinase-2 (MMP-2), a proteinase involved in angiogenesis, tumour invasion and metastasis." (PMID 24568264, 2014). "Bioinformatic analyses with miRBase, Target Scan, and Pic Tar indicated that MMP-2 regulation could be mediated by miR-29s, and evidence indicated that miR-29b is involved in tumor angiogenesis, invasion, and metastasis by mediating MMP-2 protein expression." (PMID 24886609, 2014). "We hypothesized that EIF5A2 may also affect tumor blood vessel wall remodeling or vessel structure via regulation of MMP-2 activity." (PMID 25071013, 2014). "MMP-2, in particular, is important in the processes involved in tumor invasion." (PMID 24765144, 2014). "Furthermore, gelatinase activity in 48h-conditionned serum free media revealed that media derived from control tumor cells presented high MMP-2 and MMP-9 activity." (PMID 24961901, 2014). "However, the in vitro and in vivo studies did show MMP-2 dependent probe cleavage, retention of radioactivity in tumor tissues and slow washout from tumor tissues, indicating the possible application of the MDAP strategy." (PMID 25010662, 2014). "Furthermore, p-STAT3 can upregulate the expression of matrix metalloproteinase 2 (MMP2) to promote the formation of VM in tumor tissues." (PMID 24959290, 2014). "To confirm our in vitro findings, we examined whether suppression of MMP-2 could inhibit tumor angiogenesis using the dorsal air sac assay." (PMID 23381805, 2013). "In this meta-analysis, the MMP2-1306 C>T polymorphism was significantly associated with HNC risk both in overall comparison and in subgroup analyses based on the source of the controls and tumor sites." (PMID 23637955, 2013). "MT1-MMP, the first member of a more recently established group of MMPs containing a membrane-spanning sequence, has been shown to have an important role in MMP-2 activation in cell membranes, and its overexpression seems to have a significant effect on tumor growth." (PMID 23281640, 2013). "In vivo, YQFS induced a significant delay in tumor growth, which could be mediated by decreased expression of MMP-2/9 via the ERK pathway." (PMID 23506655, 2013). "Furthermore, when compared to Tg/Placebo group, CM treatment alone increased the expression of mmp2 (P < 0.05), which is believed to be involved in tumor angiogenesis due to its matrix-degrading capacity." (PMID 23662128, 2013). "The increased MMP-2 activity in the micrometastasis increases the expression of MMP-2 in the surrounding stromal cells and thus could promote angiogenesis and tumor growth resulting in macrometastatic androgen independent disease." (PMID 23766685, 2013). "A new chemotherapy agent that can deliver miR-29c and target integrin β1 and MMP2 may solve this problem because of the close relationship between MMP2 and miR-29c in tumor metastasis." (PMID 23936390, 2013). "This increased MMP-2 activity by way of soluble factors and/or direct contact leads to activation of pro-MMP-2 in the stroma and thus could promote angiogenesis and tumor growth." (PMID 23766685, 2013).
tumor (continued). "The artificial miRNAs, designated for targeting OPN, could significantly inhibit OPN expression in HCCLM3 cell line and result in decreased in vivo tumor growth and lung metastasis through the repression of matrix metalloproteinase 2 (MMP2) and NF-κB pathways." (PMID 24383051, 2013). "Moreover, MMP-2 promotes cell survival and proliferation by inhibiting the binding of death ligands to the surfaces of tumor cells." (PMID 24147037, 2013). "MMP-2 and -9 degrade the intercellular mesenchyme and promote tumor migration." (PMID 24137350, 2013). "To test whether increased expression of TIMP-1 induces expression of the EMT markers, we analyzed the tumor sections derived from the in vivo experiments for the expression of Snail, Slug, MMP-2, and MMP-9." (PMID 24143225, 2013). "Furthermore, LEF1 knockdown reduced tumor cell viability, invasion capacity, MMP2 and MMP-9 expression, but induced apoptosis." (PMID 24098538, 2013). "In summary, the up-regulation of claudin-6 may result in abnormal structure and function of TJs and activation of MMP-2 both of which can result in some of the highly invasive tumor cells acquiring invasive and metastatic phenotype." (PMID 24245968, 2013). "Enhanced MMP-2 secretion increases tumor survival by increasing angiogenic potential." (PMID 23381805, 2013). "CAFs with increased TAGLN expression levels may enhance tumor cell invasion and migration ability which promote an enhanced expression of MMP-2." (PMID 23510049, 2013). "Consistently, TGF-β1/H2O2/HOCl was most efficient in promoting the polymerization of actin in tumor cells and the production of active MMP-2 and MMP-9 by tumor cells in response to ECM molecules (matrigel), which are important for migratory and invasive properties of tumor cells." (PMID 24260309, 2013). "In our model, we also noted tumor cells with high MMP-2 expression." (PMID 23384043, 2013). "In mice models, the deficiency of MMP-2 results in a reduction of immature blood vessels and without neovascularization results in a reduced tumor burden." (PMID 23766685, 2013). "Furthermore, YQFS effectively retards tumor cell migration and invasion by inhibiting metalloproteinase-2/9 (MMP-2/9) expression, both in vitro and in vivo." (PMID 23506655, 2013). "Thus, our in vivo data further confirm a functional contribution of GM-CSF overexpression to tumor invasion and malignancy, together with the upregulation of collagenolytic and gelatinolytic activities by enhanced expression of MMP-2, MMP-9, and MMP-26." (PMID 23634280, 2013). "MMP-2 can also promote tumor angiogenesis by rebuilding the extracellular matrix." (PMID 24245968, 2013). "In particular, MMP-2 and -9 are important for tumor invasion and angiogenesis." (PMID 23426077, 2013). "MMP-2 and other members of the matrix metalloproteinases family are known to mediate invasion during development and metastasis, and are also regarded as putative tumor markers for clinical applications." (PMID 24386189, 2013). "Importantly, MAP kinase signaling such as ERK, JNK, p38, plays a significant role in MMP regulation, particularly MMP-2/9 in tumor cell migration." (PMID 23506655, 2013). "As MMP-9 plays an important role in tumor metastasis, gelatinase activity (indicating the activity of MMP-2 and MMP-9) was assessed by in situ zymography, which is a unique technique for revealing proteolytic activity at specific sites in tissues or cell cultures." (PMID 23862139, 2013). "Although reactive astrocytes surrounding brain metastases has been observed our data suggests a novel mechanism by which tumor cells when conditioned with astrocyte secretome (MMP-2 and -9) becomes highly migratory and invasive leading to tumor cells metastasis to the brain and other sites." (PMID 24324647, 2013). "MMP-2, MMP-9, and other members of the MMP family have been associated with tumour progression." (PMID 23566419, 2013).
tumor (continued). "Moreover, immunohistochemical analysis demonstrated that the expression level of MMP-2 in tumor tissues formed by A549 LACSLCs was higher than that of tumors formed by A549 monolayer cells." (PMID 24386189, 2013). "As an initial step of our study, we observed that tumor-conditioned medium from irradiated 4910 and 5310 cells enhanced capillary tube formation in ECs as compared to control-CM, which correlated with high MMP-2 and SDF-1 expression levels." (PMID 23381805, 2013). "MMP-2 has been considered essential for metastasizing tumor cells." (PMID 23281640, 2013). "In the case of border positive micrometastasis the variable stromal cell expression of MMP-2 may be explained by possible tumor cell factors stimulating the production of MMP-2 in both tumor and stromal cells." (PMID 23227342, 2012). "Furthermore, we showed that MMP-2 inhibition strongly limited the tumor cell migration both in the agarose drop model and the transwell assay." (PMID 22848537, 2012). "Subsequently, we explored the potential molecular mechanisms through which osteoblast derived MMP-2 could control tumor survival." (PMID 22238668, 2012). "This increased tumor growth and metastasis formation could be attributed to the IL-8-mediated up-regulation of the metalloproteinases MMP-2 and MMP-9 expression and activity." (PMID 22811704, 2012). "In addition to these essential roles in the early steps of tumor metastasis, MMP-2 activation promotes angiogenesis, one of the prerequisites for metastatic tumor growth." (PMID 22408395, 2012). "Matrix metalloproteinase-2 (MMP-2) is a key regulator in the migration of tumor cells." (PMID 22848537, 2012). "MMP2 is also implicated in non-physiological tissue invasion, allowing tumor cell invasion and metastasis in breast, lymph, ovarian and colorectal cancers, as well as in others." (PMID 22729485, 2012). "These include: increased expression of growth factor receptors (e.g., EGFR), elevated glucose metabolism and up-regulated glucose transporters (e.g., Glut-1) and an increased tissue proteolysis by the tumor, through upregulation of proteolytic enzymes such as MMP-2, -9 and cathepsin B and D." (PMID 22348134, 2012). "Up-regulation of TIMP-1 was shown to suppress the tumor invasion and metastasis in various human cancers, which may be correlated with its inhibition on MMP-2/9." (PMID 23029478, 2012). "In this study, we found that co-culturing the SACC-LM cells and fibroblasts to mimic the tumor-stroma interactions produced elevated levels of MMP-2 and MMP-9 and gave rise to greatly increased in vitro invasion activity of SACC-LM cells, as compared with cultures of SACC-LM cells alone." (PMID 22200897, 2012). "Meanwhile, MMP-2 activity can be activated byMMP-14, and this activity may be involved in tumor invasion and metastasis." (PMID 22992780, 2012). "Also we found that active MMP2 was present at all stages of tumor while active MMP9 just at more advanced tumors." (PMID 23304126, 2012). "To obtain some mechanistic insights, we examined whether the MMP-2 regulated adhesion of tumor cells requires αvβ3 integrin." (PMID 22848537, 2012). "This might suggest that the inhibitor or inhibitors affect both stromal and tumor cell MMP-2 expression." (PMID 23227342, 2012). "Because some effective antitumor agents targeting tumor vessel formation have been shown to reduce MMP2 activity and MMP2 produced by endothelial cells is known to contribute to the progress of angiogenesis, we investigated MMP2 enzyme activity in response to EEGS treatment." (PMID 23206527, 2012). "To verify this hypothesis, we first tested whether MMP-2 activity was involved in tumor cell adhesion." (PMID 22848537, 2012). "MMP-2 activity as determined by zymography has shown a strong correlation with tumor invasion." (PMID 22852097, 2012). "To test whether TGFβ was the principal molecule in the osteoblast conditioned media through which MMP-2 impacted tumor survival, we utilized a TGFβ neutralizing antibody (2G7)." (PMID 22238668, 2012).